RAD51 (RAD51 recombinase)
Diseases named in the same sentence as RAD51 in open-access papers (continued):
Sharing a sentence is not in itself a finding about the gene and the disease.
cancer (continued). "For instance, it has been reported that ER stress and thus activation of the UPRER induced by tunicamycin or glucose deprivation, suppresses DNA double‐strand break repair in cancer cells by stimulating the degradation of Rad51." (PMID 34190393, 2021). "Seven kinds of RAD52i have been proposed, and some of these compounds are approved by the FDA, indicating that RAD52i is an attractive approach for BRCA1-, BRCA2-, RAD51 paralog-, and PALB2-deficient cancer." (PMID 33922657, 2021). "The high levels of collagen I, C-MYC, SIRT1, COX2, and RAD51 expression in the tumor are attenuated by the treatment, leading to reduced fibrosis, viability, inflammation, culminating in cancer cell death." (PMID 34959644, 2021). "This concept is partially supported by the fact that almost all cancer tissues showed an overexpression of RAD51, as compared to the corresponding normal tissues." (PMID 34067336, 2021). "To further validate the predicted role of RAD51 in regulating autophagy-related pathways in vitro, we first checked expression levels of the RAD51 gene in various cancer cell lines." (PMID 34067336, 2021). "EME1, RECQL4, and GEN1 mRNAs were correlated strongly with high RAD51 in six, four, and two of the eight most common cancers, respectively." (PMID 34571923, 2021). "In turn, UCHL3 deubiquitinates RAD51 and promotes the binding between BRCA2 and RAD51, which play an important role in DNA damage repair and the resistance of cancer cells to radiation and chemotherapy." (PMID 34177595, 2021). "By using the EPIC, MCPCOUNTER, and XCELL algorithms, we found that CAF infiltration level was closed related to the expression profile of RAD51 in 16 of the 40 cancers from the TCGA database, with HCC being one of them." (PMID 34115569, 2021). "The polymorphisms RAD51/G135C, ATM/P1054R, and CHEK2/T470C were selected because they were associated with many cancers, such as prostate, breast, head and neck cancer, and leukemias." (PMID 33778923, 2021). "The resistance of SUM149 cancer stem cells to olaparib was reversed with RAD51 knockdown in vitro and in vivo, indicating a good potential for a combination of PARPi and RAD51i to alleviate PARPi resistance in BRCA-deficient tumors." (PMID 34208492, 2021). "In contrast, RAD51 knockdown was shown to increase the sensitivity of cancer cells to DNA-damaging agents." (PMID 34208492, 2021). "Intriguingly, the expression of the RAD51 gene was significantly upregulated in most cancers, as compared to corresponding normal controls." (PMID 34067336, 2021). "We also identified other deletions associated with higher HRD in multiple cancer types, such as XRCC2/3 and BARD1 deletion in BLCA, TP53BP1, and RAD51 deletion in OV and LUAD, and CHEK1 deletion in TCGT and SKCM, etc.." (PMID 34572800, 2021). "Rad51 expression in tumor tissues was higher than the expression in para-carcinoma tissues (P < 0.05)." (PMID 33842359, 2021). "Rad51 is seen as a promising target in the treatment of various cancers, therefore there are ongoing efforts to discover additional Rad51 inhibitors and use these results in future clinical trials." (PMID 32719412, 2020). "To delineate any potential role for PTEN in the regulation of the RAD51/HR-dependent activity, we used a systematic approach to evaluate RAD51 expression, DNA repair activity, and PARPi responses in diverse PTEN-deficient primary and cancer cell models." (PMID 33138032, 2020). "It remains to be determined how the different roles of RAD51 during HR and replication uniquely contribute to cancer." (PMID 33015624, 2020). "If pretreated with both inhibitors, 681641 and R1-1, a Rad51 inhibitor, further enhanced apoptosis was seen in cancer cells." (PMID 32355263, 2020). "Developing RAD51 modulators that are safe and effective for clinical use is an exciting approach to target cancer." (PMID 33015624, 2020).
cancer (continued). "It has been shown in other cancer cells that RAD51 expression can be transcriptionally regulated by various signaling pathways, including regulation by the MAPK signaling pathway and downstream effectors such as cMyc or EGR and Elk120–23." (PMID 32719412, 2020). "Experimental evidence has demonstrated that Wee1 inhibitor AZD1775 significantly inhibits cancer growth and impairs RAD51 focus formation in response to radiotherapy." (PMID 32355263, 2020). "In summary, we show that small molecule inhibitors of RAD51 have the potential to increase cancer cell killing while reducing/minimizing genomic instability caused by chemotherapy." (PMID 32968740, 2020). "Functional biomarkers of HRD have also been developed, such as the assessment of RAD51 foci assembly in cancer cells, which is known to correlate with proficient homologous recombination." (PMID 32193378, 2020). "In contrast to this, monoallelic variants of the RAD51 gene and of five of its paralogs have recently been involved in cancer predisposition: RAD51B, RAD51C, and RAD51D in OC; RAD51, RAD51B, and XRCC2 in BC." (PMID 32046255, 2020). "Overexpression of HRR genes, in particular RAD51 and genes that promote the formation of Rad51 filaments is frequently observed in different cancer cells at both protein and transcript levels." (PMID 32719412, 2020). "In EOT biopsies, RAD51 foci deficiency was identified in 77% (17/22) locally assessed TNBC, as well as an ER-positive BRCA2 mutant control cancer." (PMID 32471999, 2020). "Maintaining appropriate levels of RAD51 expression and activity is critical for HR and thus cancer prevention." (PMID 33015624, 2020). "BRD4 inhibition induces HR deficiency independent of the BRCA status by impairing CTIP, BRCA1, and RAD51 expression, inducing DNA damage and eventually resulting in mitotic catastrophe in various cancer cell lines and PDX models." (PMID 32029455, 2020). "One of the most robust markers of defective HR in cancer is elevated mRNA expression of RAD51, an ATPase central to HR repair." (PMID 33489883, 2020). "RAD51 is one of the key proteins of the HR pathway that is often overexpressed in cancer cells, notably in PDAC, and is thus now considered a clinically relevant target for combined therapies." (PMID 32635552, 2020). "BRAF, especially the mutant type BRAFV600E, has been found to enhance cancer radioresistance by promoting DNA repair by stimulating 53BP1 and RAD51." (PMID 33228740, 2020). "As a result, compounds that alter RAD51 activity are being developed as novel cancer therapeutic targets." (PMID 33015624, 2020). "Most importantly, HDACis are involved in DSB repair through prolonged expression of γH2AX and therefore downmodulate RAD51 and DNA-PK expression, eventually sensitizing cancer cells to IR367,368." (PMID 32355263, 2020). "This was evidenced by substantial decrease of Rad51 foci that were co-localized with γ-H2AX when cancer cells were treated with Dox in presence of AKT inhibitor." (PMID 33266502, 2020). "B02 is a RAD51 inhibitor which interferes with ssDNA binding ability and has proved to sensitize cancer cells to several DNA damage agents in preclinical studies also in combination with PARP inhibitors." (PMID 32932697, 2020). "RAD51 is also highly expressed in many cancers and has been identified as a radiosensitive target for many cancers." (PMID 32391047, 2020). "Again, our data is in a close consistency with the data published recently by Mueck C. with co-authors illustrating that knockdown of Akt1 significantly reduced the amount of Rad51 protein in the nuclear fraction of irradiated non-small ling cancer cells." (PMID 33266502, 2020). "This compound specifically works on those cancer cells where RAD51 is overexpressed, sensitizing them to chemo/radiotherapy and PARP inhibitors." (PMID 32932697, 2020). "Due to its central role in HR, a pathway which cancers frequently become addicted to, RAD51 has also unsurprisingly been a target for inhibitor studies." (PMID 36046263, 2020).
cancer (continued). "Since RAD51 misregulation contributes to cancer and resistance to therapy, pharmacologically modulating RAD51 activity is an active area of research." (PMID 33015624, 2020). "This review will focus on the role of RAD51 in cancer and beyond and how modulation of its function can be exploited as a cancer therapeutic." (PMID 33015624, 2020). "As indicated, the inhibition of important HR repair components, such as recombinase RAD51, provides promising results in terms of sensitizing cancer cells to radiotherapy." (PMID 32650508, 2020). "For example, we demonstrate that VPA and MS-275 diminish the expression levels of RAD51, which is a key HR protein and a survival factor for cancer cells harboring damaged DNA." (PMID 31932908, 2020). "We asked next, how general is the correlation between FOXM1 expression and markers for replication stress (pS345 Chk1 and/or pS428 ATR) and FOXM1 transcriptional targets Cyclin B and RAD51 in cancer cell lines and tumor samples." (PMID 33253193, 2020). "Pin1 also enhances BRCA1-BARD1 interaction with RAD51, thereby increasing the presence of RAD51 at stalled replication structures and governing replication fork protection during cancer development." (PMID 32296699, 2020). "The human protein Rad51 is double-edged in cancer contexts: on one hand, preventing tumourigenesis by eliminating potentially carcinogenic DNA damage and, on the other, promoting tumours by introducing new mutations." (PMID 37528958, 2020). "When Dox-treated cells were washed out (to exclude a permanent DNA damage), we found a substantial increase of Rad51 intensity in cancer cells." (PMID 33266502, 2020). "RAD51 overexpression in cancer has been usually reported, and has induced poor prognosis, particularly in CRC." (PMID 31973027, 2020). "Conversely, inhibiting or downregulating HDR proteins such as RAD51 can sensitise cancer cells to genotoxic agents by preventing DSB repair, thereby suppressing tumour growth." (PMID 32797168, 2020). "Not surprisingly, several studies have demonstrated that many cancers, including carcinomas of the lung, upregulate RAD51 to compensate for defective HR pathways." (PMID 33489883, 2020). "Functional analysis and characterization of these VUS will give insight into RAD51’s role in not only cancer, but FA-like syndrome as well." (PMID 33015624, 2020). "Strikingly, a substantial decrease of Rad51 foci-positive cells was found when cancer cells were treated with Dox in combination with MK-2206." (PMID 33266502, 2020). "As overexpression of RAD51 stimulates cancer aggressiveness, it has been shown that lowering its expression or activity (through inhibition) can sensitize cancer cells to chemotherapeutics." (PMID 32932697, 2020). "This similarly impaired RAD51 foci formation, and was also shown to sensitize cancer cells to mitomycin C." (PMID 36046263, 2020). "Finding the right balance of RAD51 activity is critical for maintaining genome stability and cancer prevention." (PMID 33015624, 2020). "Across four cancer cell lines, increased ROS due to RAD51 depletion correlated with reduced cell numbers, although that was not paralleled in BRCA1-depleted cells." (PMID 32572160, 2020). "Because RAD51 is an integral component of the cellular DNA damage response, its suppression sensitizes cancer cells to DNA-damaging drugs." (PMID 31640742, 2019). "Rad51-mediated homologous recombination is the major mechanism for repairing DNA double-strand break (DSB) repair in cancer cells." (PMID 30894431, 2019). "IMPORTANCE Rad51-mediated homologous recombination is the major mechanism for repairing DNA double-strand break (DSB) repair in cancer cells." (PMID 30894431, 2019). "Rad51 is a multifunctional protein involved in DNA replication and homologous recombination repair and plays a significant role in cancer development." (PMID 31327760, 2019). "It is worthwhile to note that only FOXM1, E2F1, and RAD51 showed positive correlations with UBE2C in all 27 cancers." (PMID 31067633, 2019).
cancer (continued). "Dysregulation of RAD51 is capable of impairing HR and inducing aberrant genome rearrangements, genetic phenomena that can be seen in a variety of cancers." (PMID 30975222, 2019). "The central activities of RAD51 in DNA repair and replication point toward a role in cancer and cancer therapy chemoresistance." (PMID 31375703, 2019). "It was demonstrated in the literature reports that the 135G/C and Q356R polymorphisms of RAD51 and BRCA1 genes, respectively, were associated with an increased risk of cancer and influenced the histological malignancy grading." (PMID 30712190, 2019). "Inspired by these observations, we examined the contribution of RAD51 to cancer cell metabolism, especially the glycolysis process." (PMID 31889908, 2019). "Further development would be needed to appropriately clarify the molecular mechanisms of the RAD51 and its influence in BC in order to develop new anti-cancer therapy." (PMID 30975222, 2019). "Others studies showed that TSA, vorinostat and abexinostat can repress BRCA1 (Breast Cancer 1) and RAD51 (Recombination Protein A) expressions and thereby inhibit the homologous recombination and the non-homologous recombination end joining DDR mechanisms." (PMID 31658720, 2019). "In order to resist antitumor DNA damage reagents, cancer cells usually rely on Rad51-dependent homologous recombination to repair DNA." (PMID 32083122, 2019). "Underscoring the importance of the coordination of RAD51 activity by BRCA2, BRCA2 mutations in the BRC repeats have been found in cancers." (PMID 30551670, 2018). "Future basic and clinical studies are required to uncover how the RAD51 mediators function to prevent cancer and develop targeted therapies toward the tumor-harboring mutations in these critical regulators." (PMID 30551670, 2018). "RAD51 inhibitors show promise for treating cancers, especially for those that exhibit elevated levels of RAD51 expression." (PMID 31435521, 2018). "RS-1 stimulates RAD51 DNA binding and recombination activities (locking it into its active conformation), and RS-1 induces synthetic lethality in RAD51 overexpressing cancer cells." (PMID 29757235, 2018). "In contrast to other vertebrate models, knockdown of RAD51 paralogs in human cancer cell lines (HeLa, HT1080, MCF7, and U2OS) has been challenging." (PMID 30551670, 2018). "Overall, this work unveils the RAD51 assay as a functional biomarker to improve patient selection for PARPi monotherapy in other cancers and beyond the gBRCA condition, including those with PALB2 mutation." (PMID 30377213, 2018). "We found that XRCC2 expression is upregulated in nearly all types of cancers, to a degree comparable to RAD51 while much higher than RAD51C." (PMID 29549248, 2018). "Here, we discuss the current perspective on the in vivo and in vitro function of the RAD51 paralogs, and their relationship with cancer in vertebrate models." (PMID 30551670, 2018). "Here we identified the ~2.1 kb promoter of XRCC2, similar to ~6.5 kb RAD51 promoter, as also hyperactivated in cancer cells." (PMID 29549248, 2018). "One such strategy is to target tumors with cancer-specific, hyperactive promoters of HR genes including RAD51 and RAD51C." (PMID 29549248, 2018). "The BRCA2 protein can regulate homologous recombination by interacting with the RAD51 recombinase, and many studies have suggested that the rs144848 polymorphism in the BRCA2 gene is a susceptibility locus for cancers." (PMID 28418854, 2017). "We have recently demonstrated that silencing PLAUR affects phosphorylation of RAD51 and impairs HR pathway in cancer cells." (PMID 29254187, 2017). "In the entire cancer series, prelamin A and RAD51 levels were 2.2 ± 0.14 and 2.4 ± 0.12 (mean ± SEM)." (PMID 29212225, 2017).
cancer (continued). "Recent reports reveal that prelamin A–processing defects play a role in cancer development by impacting on transcription of key players in the maintenance of the genome stability, including RAD51." (PMID 29212225, 2017). "SAHA inhibited radiation-induced upregulation of RAD50 and RAD51 in diverse types of cancer cells, suggesting a possible role of impaired homologous recombination (HR) repair pathway in SAHA-induced radiosensitization." (PMID 29118323, 2017). "Rad51 nucleofilament assembly requires the help of mediator proteins, such as breast cancer 1 and 2 (BRCA1 and BRCA2) and several Rad51 paralogues, but the exact mechanisms that underlie this process are only partially understood." (PMID 28471392, 2017). "In an experimental model system, cancer stem cells in BRCA1 mutant TNBC which were resistant to PARP inhibition showed higher RAD51 expression." (PMID 29287594, 2017). "We propose that RAD51 G151D contributes significantly to the refractory phenotype of cancer cells, by conferring resistance to therapeutics as a result of its hyper-recombinant phenotype." (PMID 27513445, 2016). "Therefore, RAD51 SNPs identified in the general population may yield clues to better understand both RAD51 function and how dysfunction may lead to an increased risk of cancer and/or acquired resistance to standard of care treatments." (PMID 27513445, 2016). "Rad51 overexpression correlates with poor prognosis in many cancers, but its relationship with CNS tumors, including sPNETs, has not yet been thoroughly explored." (PMID 27074032, 2016). "PSIP1 is known to facilitate the resection step during homologous recombination mediated-repair and is required for RAD51 foci formation after DNA damage in a number of cancer cell lines." (PMID 26840454, 2016). "Numerous studies report that Rad51 is over-expressed in different cancers, elevated expression of Rad51 is correlated with decreased patient survival." (PMID 27494891, 2016). "Nonetheless, additional studies are needed to elucidate the link between RAD51 G135C and cancer etiology." (PMID 27513445, 2016). "Enhanced self-renewal of cancer stem cells and high proliferation rate of cancer progenitor cells indicate that they use RAD51-dependent HR to repair spontaneous and therapy-induced DSBs." (PMID 26784987, 2016). "Especially, gefitinib(GEFI) induced suppression of Rad51 was proved to be a novel strategy in cancer therapy." (PMID 26752698, 2016). "It had been reported that the inhibitor of RAD51 weakens HR pathway and sensitizes cancer cells to anti-tumor therapy." (PMID 27449097, 2016). "The involvement of RAD51 in the DNA repair determines its potential role in maintaining genetic stability, which is disturbed in cancer." (PMID 25743260, 2015). "Previous experiments with siRNA against RAD51 have highlighted the potential of RAD51 down-regulation at increasing radio- or chemosensitivity of cancer cells." (PMID 26610585, 2015). "Given that many human tumor cells express unusually high levels of RAD51, the results have potential implications with respect to both the mechanism of tumor progression and cancer therapy." (PMID 25765654, 2015). "Based on these analyses, we conclude that depletion of CLBC sensitizes diverse human cancer cells to the PARP inhibitor olaparib and causes defects in cellular responses to DNA double strand breaks including Rad51 foci formation and HR repair." (PMID 25883215, 2015). "RAD51 overexpression has been observed in a wide variety of cancer types and spontaneous RAD51 foci have been reported in various cancer cell lines." (PMID 25765654, 2015). "IBR2, a novel small molecule that inhibits cancer cell growth and induces apoptosis by inducing proteasome-mediated RAD51 protein degradation, significantly prolonged animal survival in a murine imatinib-resistant CML model bearing the T315I Bcr-Abl mutation." (PMID 25749979, 2015).